MIR520H (microRNA 520h)
Synonyms: hsa-mir-520h; MIRN520H
Gene: MicroRNA gene on chromosome 19 (53,742,512 to 53,742,599, forward strand). Ensembl gene ENSG00000207861.
Gene Ontology:
Biological process: miRNA-mediated post-transcriptional gene silencing